FAS (Fas cell surface death receptor)
Diseases named in the same sentence as FAS in open-access papers (continued):
Sharing a sentence is not in itself a finding about the gene and the disease.
COVID-19 (continued). "Supporting this hypothesis, patients with COVID-19 show elevated FAS expression on the T cell in plasma, which is known to be related to higher levels of caspase activation and PS exposure on the T cell and ultimately leads to T cell apoptosis, which is a feature of severe COVID-19." (PMID 37397483, 2023). "Higher FAS expression on CD4+ and CD8+ T cells was identified in patients with COVID-19 than in healthy controls." (PMID 39859379, 2025). "This ‘coloc-first’ approach identified four proteins (ABO, FAS, OAS1, THBS3) with evidence of genetic colocalisation (PP.H4 >0.8) with four out of seven COVID-19 phenotypes." (PMID 34402426, 2021). "Higher gene expression of FAS and FASL may lead to greater inflammation in COVID-19 patients, with higher levels of IFN-γ and T lymphocyte death." (PMID 39859379, 2025). "FAS gene expression levels were greater in individuals with severe COVID-19 than in those with non-severe symptoms (p = 0.0029)." (PMID 39859379, 2025). "Among individuals with non-severe COVID-19, carriers of the AA genotype for FAS rs1800682 (A/G) had higher levels of FAS expression, more symptoms, and higher IFN-γ levels (p < 0.05)." (PMID 39859379, 2025). "We found that FAS was lower in plasma from pregnant COVID-19 women when compared with those without infection." (PMID 34326336, 2021). "The analysis of COVID-19 extended interactome indicates several membrane bound gene/proteins (i.e., ICAM1, EGFR, ERBB2, APP, ADR2, FAS, CDH1, and MAPT), whose activity and/or expression could be affected by SARS-CoV-2 challenge." (PMID 33123533, 2020). "Apoptosis mediated by the FAS-FASL pathway, which is sustained by the continual stimulation of cytokines such as TNF and IL-6, may have been involved in the lymphocyte death seen in the spleens of the COVID-19 patients studied herein." (PMID 41210940, 2025). "Thus, the increased gene expression of FAS and FASL may be a determining factor for the severity of COVID-19, as it is likely that they trigger the death of T cells and thus lead to the development of lymphopenia present in patients with severe COVID-19." (PMID 39859379, 2025). "Thus, the positive correlation between the expression levels of FAS and FASL and these molecules with the levels of FN-γ suggests that an accentuated production of these components may promote the inflammatory process in the lungs and lead to the development of more intense symptoms of COVID-19." (PMID 39859379, 2025). "In patients with severe, but not mild, COVID-19, we detected the putative interaction between TNF on monocytes and different members of the TNF receptor superfamily (i.e., FAS and TNFɑR1) expressed by mature and immature neutrophils." (PMID 34548411, 2021). "A major region of this tSNE map present in COVID-19 patients, but not HDs or RDs, encompasses CD8 T cells enriched for expression of CD38, HLA-DR, KI67, CD39, and PD-1, highlighting the coexpression of these activation markers with other features, including CD95 (i.e., FAS)." (PMID 32669297, 2020).
melanoma (34 papers, 2005 to 2026). A malignant, usually aggressive tumor composed of atypical, neoplastic melanocytes. "We then engineered the melanoma cell lines with loss-of-function alterations (BAX or FAS knockdown or over-expression of a dominant-negative DFFA [DFFA-cleavage-resistant [CR]]50) that mimic deletions of pro-apoptotic genes, testing one gene at a time." (PMID 41175874, 2025). "In melanoma, we identified an 8-gene signature (CD28, CD80, CD86, CTLA4, FAS, IFNG, IL10, and IL12A) associated with survival." (PMID 42216340, 2026). "Knockdown of individual proapoptotic genes (BAX or FAS) partially rescued melanoma cell lines from T cell-induced apoptosis." (PMID 41175874, 2025). "Inhibition of proMMP-2 and proMMP-9 release from melanoma cells; significant increase in sensitivity to FAS-induced apoptosis." (PMID 39594665, 2024). "Accordingly, FAP-1 has been reported to inhibit FAS-mediated apoptosis in pancreatic adenocarcinoma and melanoma." (PMID 33003469, 2020). "A small molecule DUB inhibitor (EOAI3402143) phenocopied the FAS induction and apoptotic sensitization of Usp5 knockdown and fully blocked melanoma tumor growth in mice." (PMID 24980819, 2014). "Similar results were obtained in cells treated with IFN-α, a FAS-inducing apoptotic cytokine used in the clinical treatment of melanoma." (PMID 24980819, 2014). "WM793 melanoma cells expressed HLA class I and II and FAS, and a low percentage of the cells expressed FASL, B7-1, and B7-2." (PMID 16281981, 2005). "Our data rule out a role of Fas/Fas ligand interaction in tumor cell lysis by the CD8+ CTL line as MAb to FAS was unable to block CTL lysis of melanoma cells in spite of expression of FAS-L and FAS by the CTL and tumor cells, respectively." (PMID 16281981, 2005). "BCL10 (3.84-fold), TRADD (2.71-fold), CYCS (2.51-fold), DIABLO (2.43-fold), BAD (2.36-fold), BID (2.17-fold), TNFSF8 (2.13-fold), TNFSF10 (2.11-fold), BAX (2.03-fold), and FAS (2.01-fold) were also proapoptotic genes highly upregulated in response to UA treatment in A-375 melanoma cells." (PMID 39473730, 2024). "Interestingly, human melanoma cells silenced for FAP-1 show increased surface FAS expression and respond to recombinant FAS ligand (FasL) treatment by the induction of apoptosis." (PMID 33003469, 2020).
melanoma (continued). "In addition, depsipeptide, a potent histone deacetylase 1/2 inhibitor, enhances effector T cell function by up-regulating Perforin expression in melanoma-specific, antigen-stimulated effector T cells as well as FAS expression on B16-F10 melanoma to induce tumor cell apoptosis in vitro and in vivo." (PMID 32560120, 2020). "Inhibition of proMMP-2 and proMMP-9 release from melanoma cells (WM226-4 and SK-MEL23 cell lines) as well as an overall significant increase in sensitivity to FAS-induced apoptosis was demonstrated." (PMID 39594665, 2024). "CTL lysis of autologous melanoma cells was CD3 (T cell receptor) dependent and FAS-FAS-L, and CD1 independent." (PMID 16281981, 2005). "In addition, our results indicated that SFN enhances FAS/CD95 gene expression at 24 and 48 h, suggesting that the FAS–FASL signalling pathway also contributes to SFN-induced apoptosis in melanoma cells." (PMID 28864908, 2018). "Adenovirally expressed TIMP3 stabilzes tumor necrosis factor receptor-1 (TNF-R1), FAS, and TNF-related apoptosis, inducing ligand receptor-1 (TRAIL-R1) on melanoma cell surface, sensitizing these cells to apoptosis induced by TNF-α, anti-FAS-antibody and TRAIL." (PMID 26116372, 2015). "In addition, a vast literatures have been highlighted the aberrant promoter methylation of FAS gene in different types of cancers including Lymphomas, CXCA, melanoma, Colon, Prostatic and Lung." (PMID 25129245, 2014). "Previous studiessuggest that IL-24 selectively kills melanoma cells via an IL-20 receptor-dependentpathway that is independent of STAT3.In melanoma tumor cells, IL-24 induces IFN-α, which leads to growth inhibitionand apoptosis, possibly involving FAS-FASL and TRAIL interactions." (PMID 22569271, 2012).
hepatocellular carcinoma (32 papers, 2011 to 2025). A malignant tumor that arises from hepatocytes. "To identify compounds that inhibit SREBP activity, we used a human hepatoma Huh-7 cell line that stably expressed a luciferase reporter gene under the control of an SREBP-driven FAS promoter (Huh-7/FAS-luc)." (PMID 35610278, 2022). "Other authors discovered that AITC inhibited the activity of the sterol regulatory element (SRE)-containing FAS promoter in human hepatoma Huh-7/FAS-luc cells reducing SREBPs target gene expression as well as de novo fatty acid and cholesterol synthesis." (PMID 35163897, 2022). "It was reported that isoquercitrin-promoted AMPK activation could enhance AdipoR1 expression and inhibit SREBP-1/FAS expression, resulting in the decrease of lipid accumulation in rat hepatoma H4IIE cells." (PMID 36771140, 2023). "Through the N-syndecan/PI3K/Akt/mTORC1 pathway, PTN could promote the expression of the SREBP-1c gene, further facilitating denovo lipogenesis by up-regulating the lipogenic enzyme FAS in hepatocellular carcinoma." (PMID 30427932, 2018). "Moreover, ER stress leads to lipid accumulation through upregulation of lipogenesis-related genes SREBP-1c and FAS in normal hepatic and hepatoma cells." (PMID 27057275, 2016). "It is reported that hepatitis B virus (HBV) suppresses the expression of MICA/B on the surface of hepatoma cells and that the HBV core protein downregulates the expression of FAS." (PMID 30925759, 2019). "Moreover, some studies have revealed that HCC cells show resistance to apoptosis because of their suppression of FAS expression, and serum levels of soluble FASL in patients with hepatocellular carcinoma show potential as a clinical parameter to evaluate prognosis." (PMID 33266043, 2020). "Interestingly, in primary cultured rat hepatocytes, metformin affected neither fatty acid oxidation nor triglyceride synthesis, yet in an in vivo model of colon and hepatocellular carcinoma (HCC) with circulating cholesterol, metformin readily decreased FAS expression." (PMID 24482631, 2014). "This study suggests that the hepatitis B virus X protein (HBx) plays a significant role in the progression of hepatocellular carcinoma (HCC) and highlights the role of a protein called PTPN13, which is known to regulate FAS-induced apoptosis and NGFR-mediated proapoptotic signaling negatively." (PMID 37760479, 2023).
lupus (32 papers, 2011 to 2025). "To assess the efficacy of D-mannose in a spontaneous model of lupus, we selected B6.lpr mice, a simplified model driven by FAS deficiency." (PMID 33402096, 2021). "Here, we chose the MRL/lpr strain, which has a spontaneous FAS mutation, and recapitulates many features of lupus." (PMID 31565032, 2019). "The B6/lpr mice, which carried a Fas gene mutation and a defect in FAS-mediated apoptosis, developed lupus-like autoimmune manifestations." (PMID 27941837, 2016). "Several studies have found an association between FAS-FASL polymorphisms and autoimmune diseases, including systemic lupus erythematosus (SLE), multiple sclerosis, primary Sjogren’s syndrome, and even GBS." (PMID 29432441, 2018). "Moreover, a role for apoptosis in SLE susceptibility is plausible, since SNPs FAS-670 A/A and FASL-844 C/C (alone or combined in a digenic type of inheritance) are associated with an increased risk of lupus." (PMID 35059842, 2022). "C5a plays a role in activating the FAS/FASL axis, with C5a-induced FAS playing a role in brain vascular cell apoptosis and caspase activation in an experimental lupus model." (PMID 39409001, 2024). "Finally, variants in FAS and FASL have been reported in patients displaying multifactorial autoimmune diseases and cancer (e.g., systemic lupus erythematosus, SLE)." (PMID 35059842, 2022). "The importance of apoptotic regulation in the immune system is highlighted by the fact that higher levels of the soluble, anti-apoptotic FAS isoform are detected in patients with systemic lupus erythematosus (SLE) and mice injected with this isoform display autoimmune diseases." (PMID 28374191, 2017). "Several studies investigated the role of FAS and FASL gene polymorphisms in the etiology of SLE; however, the role of FAS and FASL gene polymorphisms in lupus has not been conclusively established." (PMID 24348139, 2013). "In terms of direct cell-to-cell contact, a prior study reported that systemically injected MSCs could induce T-cell apoptosis via the FAS/FASL pathway in both peripheral blood and bone marrow, leading to immunotolerance in systemic lupus erythematosus animals and humans." (PMID 38542230, 2024).
glioblastoma (31 papers, 2009 to 2025). The most malignant astrocytic tumor (WHO grade IV). "In glioblastoma, the pooled result of 10 datasets from SurvExpress indicated that high expression of FAS mRNA showed a tendency to be associated with OS (HR: 1.13 [1, 1.29], p=0.06, n=1377 cases)." (PMID 31942177, 2020). "In glioblastoma, FAS also recruits SRC kinase, YES, and PI3K to promote invasion." (PMID 35249111, 2022). "Silencing RBM17 induced the pro-apoptotic exon 6 inclusion splicing switch in the FAS gene; as well as cell cycle arrest and apoptosis in glioblastoma cells in vitro and decreased tumor growth in a glioblastoma xenograft model in vivo, which makes it an interesting target for treatment." (PMID 34065983, 2021). "FAS and FAS-L reduced expression was also observed in glioma stem cells (GSCs) and the use of a synthetic FAS-L, Apo010, in combination with temozolomide induced apoptosis in glioblastoma (GBM) stem-like cells." (PMID 34354950, 2021). "Inhibition of FAS signaling by APG101 prevents glioblastoma invasion, increases radiosensitivity in vitro, and increases glioblastoma patients’ responses to irradiation." (PMID 35249111, 2022). "Additionally, FAS showed no prognostic value in renal carcinoma, head and neck carcinoma, hepatic cancer, ovarian cancer, colorectal cancer or glioblastoma." (PMID 31942177, 2020). "Using RT-PCR, we confirmed that among the microvesicular transcripts shared by SW480 and glioblastoma microvesicles but not detected in mast cell microvesicles, RAB13, CXCR4, MYC, and FAS transcripts were present in the SW480-derived microvesicles." (PMID 19930720, 2009). "Interestingly, we observed dramatic upregulation of FAS-L expression in U87MG glioblastoma cells during the apoptotic commitment of these cells induced by CBD, even the role of FAS-L/FAS-mediated suicide of GBM cells was not critical, due to a low endogenous expression of FAS Receptor." (PMID 30783513, 2019).